NDUFB11 (NADH:ubiquinone oxidoreductase subunit B11)
Description:
Accessory subunit of the mitochondrial membrane respiratory chain NADH dehydrogenase (Complex I), that is believed not to be involved in catalysis. Complex I functions in the transfer of electrons from NADH to the respiratory chain. The immediate electron acceptor for the enzyme is believed to be ubiquinone.
Synonyms: CI-ESSS; Np17.3; p17.3; ESSS; Np15; MC1DN30
Tractability: Small molecule: an approved drug acts on it; a structure with a bound ligand is known. Antibody: UniProt predicts a signal peptide or a membrane-spanning region. PROTAC: ubiquitination databases record sites on it; its protein half-life has been measured.
Gene: Protein-coding gene on chromosome X (47,142,071 to 47,145,466, reverse strand). Ensembl gene ENSG00000147123.
Subcellular location: Mitochondrion inner membrane
Subcellular location (Human Protein Atlas): Mitochondria; Acrosome; Connecting piece; Equatorial segment; Mid piece; Principal piece
Pathways (Reactome):
Metabolism: Complex I biogenesis; Respiratory electron transport
Gene Ontology:
Molecular function: protein binding
Biological process: aerobic respiration; proton motive force-driven mitochondrial ATP synthesis
Cellular component: mitochondrial inner membrane; mitochondrion; respiratory chain complex I
Gene-disease validity (ClinGen):
ClinGen rates the evidence that NDUFB11 causes each of these diseases.
mitochondrial disease (X-linked): Definitive.
Homologues: Orthologues: chimpanzee NDUFB11 (99% identical), macaque NDUFB11 (92% identical), dog NDUFB11 (87% identical), rabbit NDUFB11 (84% identical), rat Ndufb11 (77% identical), guinea pig NDUFB11 (76% identical), mouse Ndufb11 (76% identical), pig NDUFB11 (67% identical), rat Ndufb11b (67% identical), mouse Ndufb11b (63% identical), zebrafish ndufb11 (37% identical), Drosophila melanogaster NP15.6 (32% identical), and 1 more.
Diseases named in the same sentence as NDUFB11 in open-access papers:
NDUFB11 is named in the same sentence as 35 diseases in open-access papers, as found by Europe PMC text mining. Sharing a sentence is not in itself a finding about the gene and the disease. The quoted sentences say what the papers report.
histiocytoid cardiomyopathy (4 papers, 2017 to 2023). Histiocytoid cardiomyopathy is an arrhythmogenic disorder characterized by cardiomegaly, severe cardiac arrhythmias or sudden death, and the presence of histiocyte-like cells within the myocardium. "NDUFB11 (OMIM *300403) variants have recently been independently proposed to cause histiocytoid cardiomyopathy (histiocytoid CM; OMIM 500000) and microphthalmia with linear skin defects syndrome (MLS; OMIM 309801)." (PMID 28050600, 2017). "Finally, patients bearing point mutations in NDUFB11 presented with histiocytoid cardiomyopathy and dilated cardiomyopathy and needed heart transplantation at the age of 6 months." (PMID 33670341, 2021). "Variants in NDUFB11, which encodes a structural component of complex I of the mitochondrial respiratory chain (MRC), were recently independently reported to cause histiocytoid cardiomyopathy (histiocytoid CM) and microphthalmia with linear skin defects syndrome (MLS syndrome)." (PMID 28050600, 2017). "Notably, mutations in NDUFB11 have also been described in patients affected only by histiocytoid cardiomyopathy without features of LSDMCA, in a male infant with lethal mitochondrial complex 1 deficiency and in sideroblastic anemia." (PMID 33670341, 2021).
atherosclerosis (2 papers, 2023 to 2025). A disease characterized by the build-up of fatty material and calcium deposition in the arterial wall resulting in partial or complete occlusion of the arterial lumen. "The observed NDUFB11 downregulation in our IS cohort implies dual pathogenic mechanisms: mitochondrial dysfunction potentiation and atherosclerosis acceleration." (PMID 41377071, 2025). "In summary, NDUFB11 and NDUFS3 are underexpressed in atherosclerosis and chronic stress, and the lower NDUFB11 and NDUFS3, the worse the prognosis." (PMID 37642954, 2023). "Validation of significant role of NDUFB11 and NDUFS3 in atherosclerosis and chronic stress using public datasets." (PMID 37642954, 2023). "Gene expression heatmap showed that the core genes (NDUFB11, NDUFS3) were lowly expressed in samples of those with atherosclerosis accompanied by chronic stress and highly expressed in the normal samples." (PMID 37642954, 2023). "The main results of this study are that NDUFB11 and NDUFS3 are underexpressed in atherosclerosis and chronic stress, and the lower the NDUFB11 and NDUFS3, the worse the prognosis." (PMID 37642954, 2023). "A heat map of the expression of core genes in the samples was plotted, and we found that the core genes (NDUFB11, NDUFS3) were lowly expressed in the atherosclerosis accompanying chronic stress samples and highly expressed in the normal samples." (PMID 37642954, 2023). "However, the relationship between NDUFB11 and NDUFS3 and atherosclerosis and chronic stress is unclear." (PMID 37642954, 2023). "NDUFB11 and NDUFS3 may serve as molecular targets for the precision treatment of atherosclerosis and chronic stress, thus providing a foundation of direction for mechanistic studies of atherosclerosis and chronic stress." (PMID 37642954, 2023). "However, the relationship between NDUFB11 and NDUFS3 and atherosclerosis and chronic stress is still unclear." (PMID 37642954, 2023). "Therefore, we speculate that NDUFB11 and NDUFS3 may play important roles in intracellular energy metabolism in atherosclerosis and chronic stress." (PMID 37642954, 2023).
cardiomyopathy (2 papers, 2017 to 2025). A disease of the heart muscle or myocardium proper. "We suggest that individuals with MLS syndrome or variants or cytogenetic abnormalities involving NDUFB11, HCCS, or COX7B should be considered at risk for histiocytoid CM and screening for evidence of malignant arrhythmias and cardiomyopathy may be appropriate." (PMID 28050600, 2017).
cognitive deficits (2 papers, 2023). "NDUFB11 (ESSS protein), located in the short arm of the X-chromosome, is essential for the assembly and activity of Complex I. NDUFB11 may play a role in the mechanism underlying cognitive deficits in children and adolescents born preterm." (PMID 37168668, 2023). "NDUFB11 and NDUFS3 were associated with necrosis, hyperplasia, inflammation, renal disease, weight loss, memory impairment, and cognitive impairment." (PMID 37642954, 2023). "The core genes NDUFB11 and NDUFS3 were found to be associated with necrosis, hyperplasia, inflammation, renal disease, weight loss, memory impairment, and cognitive impairment." (PMID 37642954, 2023). "Although there have been no reports on NDUFB11 and MDD, cognitive impairment may be a phenotype that this gene contributes to depressive disorder." (PMID 37168668, 2023).
congenital sideroblastic anemia (2 papers, 2020 to 2021). "Unbiased DNA sequencing will be necessary to find all of the mutations that might exist in various disease states, as illustrated by the mutations discovered in NDUFB11 to be associated with congenital sideroblastic anemia." (PMID 33233646, 2020).
lactic acidosis (2 papers, 2021 to 2023). Metabolic acidosis characterized by the accumulation of lactate in the body. "In this study, we identified and characterized a novel splicing variant in the NDUFB11 gene reported in a neonatal male patient with fatal hypertrophic cardiomyopathy (HCM), lactic acidosis and single CI deficiency." (PMID 36675256, 2023).
Parkinson disease (2 papers, 2018 to 2021). A progressive degenerative disorder of the central nervous system characterized by loss of dopamine producing neurons in the substantia nigra and the presence of Lewy bodies in the substantia nigra and locus coeruleus. "Next we interrogated the KEGG pathway and found the top up-regulated categories showed strong correlation with Alzheimer’s, Huntington’s and Parkinson’s diseases by enriching genes such as ATP5D, ATP5H, HSD17B10 and NDUFB11, NDUFA8, NDUFB7, NDUFS8." (PMID 29915338, 2018).
sideroblastic anemia (2 papers, 2021 to 2023). "To date, six genes have been discovered that may cause sideroblastic anemia: PUS1, YARS2, LARS2, TNRNT1, NDUFB11 and MT-ATP6." (PMID 34441767, 2021).
dilated cardiomyopathy (1 paper, 2023). Cardiomyopathy which is characterized by dilation and contractile dysfunction of the left and right ventricles. "Dilated cardiomyopathy was well documented in the family, despite most NDUFB11 mutations displaying variable clinical phenotypes somewhat different from other CI defects." (PMID 36675256, 2023).
hypertrophic cardiomyopathy (1 paper, 2023). A condition in which the myocardium is hypertrophied without an obvious cause. "In summary, we showed that a novel exonic c.338G>A variant in the nuclear NDUFB11 gene, which was predicted to be a missense variant is actually a splicing variant and is associated with mitochondrial X-linked isolated CI deficiency and neonatal lethal hypertrophic cardiomyopathy." (PMID 36675256, 2023).
optic atrophy (1 paper, 2009). A disorder characterized by loss of optic nerve fibers. "For example, the optic atrophy 2 (OPA2) linkage interval contains seven mitochondrial genes that include three known DG of which HSD17B10 is associated with optic atrophy, and three predicted DG of which two genes (NDUFB11, TIMM17B) interact with mitochondrial DG causing optic atrophy." (PMID 19390613, 2009).
prostate carcinoma (1 paper, 2021). A carcinoma that arises from epithelial cells of the prostate gland. "This analysis strategy revealed the Androgen Receptor (AR) as the top prostate cancer-specific gene hit, but the next four top-ranked hits were genes not previously associated with prostate cancer: KIF4A, MRPL13, NDUFB11, and TSR2 (top 5)." (PMID 34326322, 2021).
Thromboembolism (1 paper, 2025). The formation of a blood clot inside a blood vessel that subsequently travels through the blood stream from the site where it formed to another location in the body, generally leading to vascular occlusion at the distant site. "Clinically, NDUFB11 down-expression associates with atherosclerotic progression and adverse cardiovascular outcomes, which is particularly relevant given that 20% of IS originates from atherosclerotic plaque rupture and subsequent thromboembolism." (PMID 41377071, 2025).
cancer (3 papers, 2019 to 2021). A tumor composed of atypical neoplastic, often pleomorphic cells that invade other tissues. "Down-regulate NADH dehydrogenase expression (NDUFA6, NDUFB4, and NDUFB11) to enhance ROS production and thus promote cancer cell migration." (PMID 34888249, 2021). "In addition, the regulation of the expression of the NDUFB11 gene can regulate the programmed cell death process, so it promises to be a new target for cancer therapy." (PMID 34901000, 2021). "Recent research evidence has revealed that lncRNA ZFAS1 can encode a small peptide to down-regulate NADH dehydrogenase expression (NDUFA6, NDUFB11 and NDUFB4) to enhance ROS production, thus promoting cancer development." (PMID 34888249, 2021). "Finally, we found that the experimentally validated translated lncRNA ZFSA1 promoted cancer cell migration by elevating cellular ROS production via the expression downregulation of NADH dehydrogenase expression (NDUFA6, NDUFB4, and NDUFB11)." (PMID 31781169, 2019). "Therefore, we propose that upregulated ZFAS1 promotes cancer cell migration via elevating cellular ROS production by repressing the expression of NADH dehydrogenases, including NDUFA6, NDUFB4, and NDUFB11." (PMID 31781169, 2019).
mitochondrial disease (3 papers, 2021 to 2024). "Although not directly related to early ocular GRNs, mitochondrial disease caused by variants in HCCS, COX7B, and NDUFB11 has also been previously associated with MAC cases." (PMID 38821055, 2024).
cardiovascular diseases (1 paper, 2023). "NDUFB11 expression levels may also be involved in the development of other diseases, such as tumors, neurodegenerative and cardiovascular diseases, among others." (PMID 37642954, 2023).
infection (1 paper, 2023). The state of being infected such as from the introduction of a foreign agent such as serum, vaccine, antigenic substance or organism. "The occurrence of a macromolecular assembly (through proteins such as MED30 and NDUFB11) and cellular localization (through proteins such as FIS1) seems to occur as part of the 48-h post-infection pattern, thereby suggesting that the cells experience enormous energy expenditure." (PMID 38087340, 2023).
NDUFB11 also shares sentences with these, for which no sentence is quoted: microphthalmia (3 papers); Arts syndrome (1); depressive disorder (1); developmental delay (1); epilepsy (1); Fabry disease (1); Failure to thrive (1); frontotemporal dementia (1); heart failure (1); intrauterine growth restriction (1); memory impairment (1); multiple acyl-CoA dehydrogenase deficiency (1); myofibrillar myopathy (1); myopathy (1); optic atrophy 2 (1); OXPHOS disease (1); renal disease (1); respiratory failure (1).